SIRT1 (sirtuin 1)
Diseases named in the same sentence as SIRT1 in open-access papers (continued):
Sharing a sentence is not in itself a finding about the gene and the disease.
Obesity (continued). "Moderate polyphenol intake can reduce adipogenesis, promote fatty acid oxidation, and increase energy expenditure by activating pathways such as AMPK/SIRT1 and inhibiting PPARγ, thereby exerting anti-obesity effects." (PMID 41008164, 2025). "Our study found that obesity induces hypermethylation of the SIRT1 gene, while RRTFB intervention reduced SIRT1 methylation and significantly upregulated its expression." (PMID 40909259, 2025). "With aging, this seems to lead to insulin resistance and obesity due to the downregulation of the Sirt1-Pgc1a-Ucp2 axis." (PMID 38891115, 2024). "Over- and under-expression of SIRT1 in VMH SF-1 neurons reveals that SIRT1 protects against dietary obesity by regulating EE as well as skeletal muscle glucose uptake." (PMID 41311864, 2024). "Given the close connection between SIRT1 and cellular energy and energy homeostasis, SIRT1 has become a molecular target of interest for metabolic disorders, such as obesity." (PMID 38606478, 2024). "Yet, the prolonged duration (26 weeks) of HFD significantly reduced Sirt1 expression in all three brain subregions, indicating consequential role of obesity duration." (PMID 39230054, 2024). "Conversely, phosphorylation of SIRT1 at Ser‐46 by c‐Jun N‐terminal kinase 1 activates SIRT1 function, ameliorating hepatic steatosis in obesity." (PMID 39355507, 2024). "In summary, our study reveals that SIRT1 is vital for regulating inflammation and metabolism in obesity." (PMID 39424786, 2024). "Notwithstanding the strategies made up for improving the activity of SIRTs to cope with metabolic disorders and related afflictions (including obesity-induced male infertility), it is still not well known how SIRT1 influences semen quality." (PMID 38913627, 2024). "In adipose tissue, SIRT1 inhibits PPARγ activity, promotes lipolysis, and reduces fat storage, which is essential for the prevention of obesity and metabolic syndrome." (PMID 39199358, 2024). "Studies have shown that in obesity and type 2 diabetes models, SIRT1 expression and activity are significantly decreased, accompanied by a significant increase in ER stress." (PMID 38745862, 2024). "Accordingly, it has been reported that the therapeutic modulation of Sirt1 ameliorates obesity- and age-related endothelial dysfunction and protects against high-fat diet-induced metabolic abnormalities." (PMID 39273039, 2024). "Together, these results indicate that obesity alters mitochondrial metabolism, suggesting a link between SIRT1 and metabolism in determining DCs activation fate." (PMID 39424786, 2024). "SRT1720 has been studied as a direct SIRT1 activator in microcirculation, ameliorating obesity-induced ED by promoting antioxidant protein expression while downregulating mitochondrial-aging proteins." (PMID 39598406, 2024). "Sirtuin 1 (SIRT1) acts by regulating different targets related to metabolism, in caloric restriction and obesity animal models." (PMID 39424786, 2024). "Circulating SIRT1 levels have been found to be reduced in obesity and increased in anorexia nervosa and patients experiencing weight loss." (PMID 38732001, 2024). "Upregulation of adiponectin and SIRT-1 expression after sleeve gastrectomy in a murine model of sequential HFD-induced obesity and streptozocin-induced T2DM resulted in browning of SAT via PPARγ, PGC-1α, and UCP1 activation." (PMID 39063184, 2024). "Studies have shown that upregulating the SIRT1/LKB1/AMPK pathway can reduce obesity-induced cardiomyopathy." (PMID 38436035, 2024). "Activating the AMPK/SIRT1 pathway in the liver and white adipose tissue can reduce obesity, improve thermogenesis, and suppress inflammation, as demonstrated in a study involving male C57BL/6 mice fed a high-fat diet to induce obesity." (PMID 39044934, 2024).
Obesity (continued). "Previous evidence indicated that SIRT1 an NAD+-dependent protein deacetylase attenuates obesity, promotes fat mobilization, augments mitochondrial metabolism, regulates glucose metabolism, and also inhibits inflammatory response." (PMID 39640497, 2024). "A reduction in SIRT1 expression and activity associated with HFD-induced obesity has also been reported in various studies." (PMID 39109269, 2024). "In this regard, the study by Baur and colleagues links SIRT1 to a better outcome in obesity, whereas the activation of SIRT1 by resveratrol (RES) promoted beneficial effects in HFD subjects." (PMID 39424786, 2024). "In conclusion, our findings indicate that GC attenuates obesity‐related muscle wasting by improving mitochondrial function and biogenesis via the activation of SIRT1/PGC1α in the skeletal muscle of mice." (PMID 39055231, 2024). "Elevations in NNMT and its metabolite MNAM are known to stabilize SIRT1, a critical regulator of gluconeogenesis, cholesterol synthesis in the liver, and defenses against diet-induced obesity." (PMID 39489776, 2024). "Previous studies have shown that agrimol B can alleviate obesity and related dysfunction by upregulating the expression of the antioxidant protein Sirt1." (PMID 38404180, 2024). "SIRT1 is a nuclear master regulator of energy homeostasis, and its concentrations measured in serum are reduced in obesity and increased in AN." (PMID 38732001, 2024). "Yet, the consequences of decreased SIRT1 in immune cells in obesity need clarification, especially the mechanisms involved in reprogramming DCs towards a pro-inflammatory phenotype, a hallmark of this condition." (PMID 39424786, 2024). "According to data from the literature resveratrol and others sirtuin 1 activators have demonstrated promising outcomes in a wide range of age-related diseases including obesity, diabetes, inflammation, cardiovascular disease, among others." (PMID 38529393, 2024). "Individuals with obesity exhibit markedly reduced microvascular SIRT1 expression and increased inflammation." (PMID 39598406, 2024). "Here, we report that SIRT1 expression was indeed downregulated in DCs in an experimental model of obesity." (PMID 39424786, 2024). "Inflammation triggered by obesity downregulates the expression and activity of Sirtuin 1 (SIRT1) in adipocytes, monocytes and neurons." (PMID 39424786, 2024). "Adiponectin and SIRT-1 exist in a positive feedback loop and are suppressed in obesity due to ER stress, DNA damage, NAD+/NADH redox imbalance, and cellular senescence." (PMID 39063184, 2024). "Semaglutide, in an obesity model in mice, was found to improve skeletal muscle atrophy by activating SIRT1." (PMID 39728000, 2024). "SIRT1 plays multifaceted roles in obesity including the regulation of inflammation by inhibiting nuclear factor κ-B (NF-κB), thereby reducing inflammatory responses and improving insulin sensitivity." (PMID 39707172, 2024). "This study highlights that SIRT1 controls the metabolism and functions of DCs through modulation of the kynurenine pathway, with significant implications for obesity-related inflammation." (PMID 39424786, 2024). "In line with obesity and reduced expression of the Sirt1-Pgc1a-Ucp2 axis, we found that Chr4Δ70/Δ70 mice also developed insulin resistance during aging." (PMID 38891115, 2024). "Obesity directly affects SIRT1 activity through a deficit in catabolism, which is clearly responsible for the de novo NAD+ pathway." (PMID 39424786, 2024). "To address if SIRT1 is intrinsically impacted in DCs during obesity, we first demonstrated that the Sirt1 gene expression was downregulated in bone marrow-derived dendritic cells (BMDCs) from mice under a high-fat diet (HFD) (hereafter, BMDCs/HFD)." (PMID 39424786, 2024). "Studies on SIRT1 have primarily focused on diseases such as obesity; however, SIRT1 has also been found to regulate lipid metabolism gene expression through a series of signaling pathways." (PMID 39337411, 2024).
Obesity (continued). "The data reported in the present study support the fundamental interdependence between full SIRT1 expression and melatonin allowing the latter to exert its antioxidant and anti-inflammatory role in obesity." (PMID 38255934, 2024). "The anti-aging gene Sirtuin 1 is important to the prevention of age-related diseases such as obesity, CVD and MASLD." (PMID 39403588, 2024). "Mechanistically, miR-22 directly targets crucial genes involved in regulating metabolism and obesity, such as the peroxisome proliferative-activated receptor (Pgc-1α), the peroxisome proliferator-activated receptor α (PPARα), and sirtuin 1 (Sirt1)." (PMID 39596297, 2024). "Conversely, decreased SIRT1 expression has been reported in individuals with metabolic syndrome, insulin resistance, or obesity." (PMID 38792610, 2024). "Collectively, these findings strongly suggest that arriheuk extract regulates browning in 3T3-L1 white adipocytes by triggering the AMPK/SIRT1 pathway, indicating the prospective applications of arriheuk as a functional food to control obesity." (PMID 37509819, 2023). "In vitro and in vivo studies of Tecomella undulata ethyl acetate extract revealed anti-obesity efficacy by downregulating adipogenesis and lipogenesis via sirtuin 1 (SIRT1), adiponectin, and peroxisome proliferator activated receptor γ (PPARγ)." (PMID 36834657, 2023). "There are seven types of SIRTs, from SIRT1 to SIRT7, of which SIRT1 is linked to obesity and controls the genetic expression of insulin secretion and sensitivity and adipose tissue formation and facilitates inflammatory responses." (PMID 38203349, 2023). "A recent study specifically investigated the role of SIRT1 in age- and obesity-related microvascular dysfunction in humans." (PMID 38304233, 2023). "SIRT1 has been used as a therapeutic target in preventing obesity-related IR in childhood and adolescence, and similar treatment is considered for type 2 diabetes." (PMID 37511397, 2023). "In young mice, SIRT1 overexpression in the liver prevents obesity-induced liver ER stress and insulin resistance." (PMID 38034869, 2023). "For example, the PARP1 activity was sufficiently robust to diminish SIRT1 activity as a direct result of depletion of NAD+ pools in diet-induced obesity." (PMID 37165408, 2023). "In patients with obesity, intracellular targets such as the deacetylating enzyme sirtuin-1 (SIRT-1), adenosine monophosphate-activated protein kinase (AMPK), and peroxisome proliferator-activated receptor γ coactivator-1α (PGC-1α) are altered." (PMID 37375898, 2023). "The SIRT1 gene, encoding an NAD+-dependent histone deacetylase, is pivotal in obesity, regulating energy homeostasis, glucose metabolism, and lipid utilization." (PMID 37862340, 2023). "The results showed that SIRT1 is directly involved in the earliest age- and obesity-induced microvascular damage." (PMID 38304233, 2023). "In this context, resveratrol can activate the SIRT-1 gene, which plays an important role in mitochondrial activity modulation, glucose homeostasis, and other metabolic conditions related to obesity." (PMID 37375898, 2023). "The current study aims to investigate the anti-obesity effects of a tea mixture nano-formulation by targeting the AMPK/Sirt-1/GLUT-4 axis in rats." (PMID 37512578, 2023). "Low SIRT1 expression in SAT of subjects with obesity has been shown and circulating SIRT1 was reported to be inversely correlated to epicardial fat thickness in patients with obesity." (PMID 37730614, 2023). "Less inflammation, improved glucose tolerance, and virtually total protection against hepatic steatosis are the advantages of SIRT1 over-expression, indicating that SIRT1 is crucial in preventing the adverse metabolic effects of obesity." (PMID 38116204, 2023).
Obesity (continued). "CD38 inhibition by flavonoids including apigenin and quercetin also improves glucose homeostasis and promotes fatty acid oxidation in the liver of mice with high-fat-diet-induced obesity, possibly through the activation of sirtuins such as Sirt1 and Sirt3." (PMID 36831262, 2023). "Sirtuin 1 (SIRT1) is one of the most important indicators in metabolic control and prevention of obesity and weight gain, and subsequent diseases such as metabolic syndrome, hypertension, type 2 diabetes, and heart diseases." (PMID 37858156, 2023). "During normal eating conditions, SIRT-1 in adipose tissue protects against inflammation and obesity, and prevents metabolic dysfunction during dietary stress." (PMID 36875756, 2023). "Treatment with melatonin has been shown to activate the SIRT1 signaling and restore autophagy and mitochondrial dynamics in obesity-induced hepatic steatosis." (PMID 37627494, 2023). "In obesity, an increased number and size of adipocytes are related to a decreased SIRT1 level and activity." (PMID 38304233, 2023). "Our recent work revealed significant elevation in PPARγ acetylation levels in aging and obesity, in which SirT1 activity was diminished." (PMID 37408258, 2023). "Whole-body SIRT1 overexpression protects against genetically-induced obesity and from age-induced glucose intolerance." (PMID 38116204, 2023). "The importance of SIRT1 has been recognized in obesity and related disorders, especially when its levels are reduced in white AT of HFD mice because it is cleaved by inflammation-activated caspases." (PMID 37432552, 2023). "We additionally investigated the in vivo effect of a nano-sized herbal tea mixture on obesity induced by a high-fat diet in rats in an attempt to provide insight into their molecular mode of action by targeting the AMPK/Sirt-1/GLUT-4 axis." (PMID 37512578, 2023). "SIRT1 has also been found to play a crucial role in the development of obesity- and age-related vascular dysfunction." (PMID 38304233, 2023). "Consistent with the results of this study, others have shown that diabetes and obesity reduce the expression of Sirt1, Sirt2, Sirt3, and Sirt6." (PMID 38134189, 2023). "Corylin also reduces obesity and insulin resistance and promotes adipose tissue browning through sirtuin 1 (SIRT1) and β3-Adrenergic receptors." (PMID 37266148, 2023). "This highlights the pivotal role of SIRT1-mediated deacetylation in preventing obesity-related metabolic syndrome." (PMID 37862340, 2023). "miRNA can mediate obesity-induced endothelial dysfunction by affecting gene expression of endothelial nitric oxide synthase (eNOS), Sirtuin 1 (SIRT1), oxidative stress, autophagy machinery, and endoplasmic reticulum (ER) stress." (PMID 37762217, 2023). "Sirt1 plays a positive role in metabolic disorders such as obesity and T2DM through deacetylating FOXO1 to alleviate oxidative stress." (PMID 37329278, 2023). "In obesity, SIRT1 counteracts obesity-induced inflammation in macrophages by deacetylating the p65 subunit of the NF-κB transcription factor." (PMID 38304233, 2023). "There are many molecular signaling pathways in the pathogenesis of obesity, including TLRs, NF-κB, GPCRs, and SIRT1." (PMID 36141228, 2022). "Our findings suggest the involvement of the IRE1α sulfonation-SIRT1 degradation axis in the anti-obesity effects of GABA and FCLL-GABA." (PMID 35458241, 2022). "The present data indicated the central role of SIRT-1 in the anti-obesity effects of SPIONs, as it was significantly upregulated in the WAT and BAT of obese rats treated with SPIONs." (PMID 36297569, 2022). "The decay of SIRT1 as a RIDD target gene is suggested to be the key mechanism involved in the attenuation of obesity conditions, along with a well-established SIRT1-PGC-1α-linked UCP1-associated energy controlling mechanism." (PMID 35458241, 2022).
Obesity (continued). "Sirtuin 1 is critical to the prevention of obesity, IR, cognition, and neurodegenerative diseases due to its role in metabolic activity, inflammation, and chronic diseases." (PMID 35873818, 2022). "Under conditions of energy excess, such as nutritional excess or early-onset obesity, SIRT1 is prematurely evicted from the promoter of KISS1, which promotes KISS1 expression, causing early puberty." (PMID 36046800, 2022). "Enhancing the function of AMPK/Sirt-1 can reduce adipogenesis and inflammation in obese mice induced by a high-fat diet, enhance antioxidant function, and have potential anti-obesity effects." (PMID 35889753, 2022). "miR-34a also targets SIRT1, which is pharmacologically beneficial for obesity disorders since it has been shown that SIRT1 activity increases oxidative metabolism as well as mitochondrial function." (PMID 36517853, 2022). "In summary, the present study demonstrates that diet-induced obesity leads to vascular dysfunction, which is associated with reduced SIRT1 activity in PVAT despite (compensatorily) enhanced SIRT1 expression." (PMID 35326191, 2022). "SIRT1 has been shown to protect against obesity; indeed, the ablation in animal model of SIRT1 in adipocyte or macrophages exacerbates obesity-induced metabolic dysregulation." (PMID 35247131, 2022). "The patients with obesity showed the lowest SIRT1 and TBS values and the highest sclerostin concentrations; BMD increased with FM and BMI and had an inverse association with SIRT1." (PMID 35267956, 2022). "Similar to previous studies, in both aging and obesity, the level of SIRT1 was abnormally reduced in skeletal muscle." (PMID 35382382, 2022). "These significant observations indicate that ER-localized Nox4-induced IRE1α sulfonation results in the decay of SIRT1 as a novel mechanism behind the positive implications of GABA on obesity." (PMID 35458241, 2022). "Accordingly, emerging evidences suggest that dysregulation in SIRT1-mediated autophagy is involved in the onset and development of obesity, type-2 diabetes mellitus, and diabetic cardiomyopathy." (PMID 35909524, 2022). "In other studies, a potent small molecule activator of SIRT1 reduced blood glucose and improved insulin sensitivity in mice with diet-induced obesity." (PMID 36030228, 2022). "The results showed that BS21 treatment dramatically upregulated the mRNA expression of SIRT1 (Sirt1), PGC-1α (Ppargc1a), and FNDC5/irisin (Fndc5), due to increased muscle weight loss by obesity." (PMID 35276805, 2022). "It was the first report to indicate that sesamol could alleviate obesity and its related metabolic disorders via regulating glucose and lipid metabolism of skeletal muscle in the middle-aged mice, which might be associated with the stimulation of the SIRT1/AMPK pathway." (PMID 35382382, 2022). "The implications of the dysregulated SIRT1 function and autophagy in endocrine disorders, including obesity, type-2 diabetes mellitus, diabetic cardiomyopathy, and hepatic steatosis will be discussed." (PMID 35909524, 2022). "Studies have demonstrated that inhibition of POMC neurons by melanin-concentrating hormone (MCH) through the SIRT1/FoxO1 pathway resulted in hyperphagia and obesity." (PMID 35873818, 2022). "Silent mating-type information regulation 2 homolog 1 (SIRT1) is a key regulator of obesity-related metabolic pathways, and its deletion leads to obesity, metabolic dysregulation, and IR." (PMID 35529922, 2022). "Deregulation of which Sirtuin 1 results in diverse biological consequences including neurodegeneration, inflammation, age-related disorders, heart diseases, obesity, and cancer." (PMID 36014823, 2022). "MiR‐199a‐5p, which is down‐regulated in sarcopenia and obesity, targets and suppresses Sirt1,56, 58 which is responsible for the deacetylation of FOXO; suppression of Sirt1 results in cellular senescence in vitro." (PMID 34984856, 2022).